IL10RB (interleukin 10 receptor subunit beta)
Description:
Shared cell surface receptor required for the activation of five class 2 cytokines: IL10, IL22, IL26, IL28, and IFNL1. The IFNLR1/IL10RB dimer is a receptor for the cytokine ligands IFNL2 and IFNL3 and mediates their antiviral activity. The ligand/receptor complex stimulate the activation of the JAK/STAT signaling pathway leading to the expression of IFN-stimulated genes (ISG), which contribute to the antiviral state.
Synonyms: IL-10RB; CRF2-4; IL-10R2; CDw210b; CRFB4; D21S58; D21S66; IBD25
Tractability: Antibody: its Gene Ontology location is reachable by antibodies, with high confidence; UniProt predicts a signal peptide or a membrane-spanning region. Other modalities: a drug acting on it is in phase 2 or 3 trials.
Gene: Protein-coding gene on chromosome 21 (33,266,363 to 33,311,420, forward strand). Ensembl gene ENSG00000243646.
Subcellular location: Membrane
Subcellular location (Human Protein Atlas): Cytosol
Pathways (Reactome):
Immune System: Interleukin-10 signaling; Interleukin-20 family signaling; Other interleukin signaling
Gene Ontology:
Molecular function: coreceptor activity; protein binding; interleukin-10 receptor activity; signaling receptor activity
Biological process: interleukin-10-mediated signaling pathway; positive regulation of cellular respiration; positive regulation of receptor signaling pathway via JAK-STAT; acute-phase response; cell surface receptor signaling pathway via JAK-STAT; cellular response to virus; cytokine-mediated signaling pathway; immune response; inflammatory response; negative regulation of inflammatory response; positive regulation of cell population proliferation; positive regulation of tyrosine phosphorylation of STAT protein; signal transduction; type III interferon-mediated signaling pathway
Cellular component: interleukin-10 receptor complex; receptor complex; interleukin-28 receptor complex; membrane; plasma membrane
Genetic constraint (gnomAD): Loss-of-function variants: 30 observed, 38.65 expected, observed/expected ratio (o/e) 0.78, 90% interval 0.58 to 1.05. The upper end of that interval is the gene's LOEUF score, 1.05, which puts it in group 4 of 6, group 1 being the genes least tolerant of losing a copy. Missense variants: 327 observed, 408.06 expected, observed/expected ratio (o/e) 0.8, 90% interval 0.73 to 0.88. Synonymous variants: 142 observed, 150.35 expected, observed/expected ratio (o/e) 0.94, 90% interval 0.82 to 1.09.
Gene-disease validity (ClinGen):
ClinGen rates the evidence that IL10RB causes each of these diseases.
inflammatory bowel disease 25 (autosomal recessive): Definitive.
Homologues: Orthologues: chimpanzee IL10RB (99% identical), rabbit IL10RB (82% identical), pig IL10RB (78% identical), dog IL10RB (78% identical), guinea pig IL10RB (76% identical), rat Il10rb (70% identical), mouse Il10rb (69% identical), tropical clawed frog il10rb (31% identical), zebrafish crfb4 (22% identical). Paralogues in human: IFNAR1 (24% identical), IFNGR2 (21% identical), IL20RA (21% identical), IFNGR1 (19% identical), IL10RA (17% identical), IFNLR1 (17% identical), IL20RB (17% identical), F3 (15% identical), IL22RA1 (15% identical), IFNAR2 (14% identical), IL22RA2 (14% identical).
Diseases named in the same sentence as IL10RB in open-access papers:
IL10RB is named in the same sentence as 128 diseases in open-access papers, as found by Europe PMC text mining. Sharing a sentence is not in itself a finding about the gene and the disease. The quoted sentences say what the papers report.
COVID-19 (24 papers, 2021 to 2025). A disease caused by infection with severe acute respiratory syndrome coronavirus 2. "For example, carriers of the rs9976829 variant which is located close to the IL-10RB locus have a higher susceptibility to COVID-19." (PMID 38455043, 2024). "In a recent genome-wide study, IL10RB was identified as the top key regulator of COVID-19 host susceptibility, with higher IL10RB expression in patient blood being associated with worse COVID-19 outcomes." (PMID 36160003, 2022). "We established a direct significant association between observed blood IL10RB expression and severe COVID-19 outcomes, including end-organ damage." (PMID 36064543, 2022). "Toward validating IL10RB as a suitable molecular target, we established a direct association between increased IL10RB GReX and expression with worse COVID-19 clinical outcomes and death." (PMID 36064543, 2022). "Our study confirms that IFNAR2 is important for COVID-19 susceptibility; however, we prioritized IL10RB over IFNAR2 as a suitable gene target for novel therapeutic development." (PMID 36064543, 2022). "Overall, in addition to predisposing individuals to COVID-19-related hospitalization and outcome severity, increased IL10RB and decreased IFNAR2 GReX are associated with respiratory failure independent of COVID-19 exposure." (PMID 36064543, 2022). "We found that severe COVID-19-risk variants in the IFNAR2 locus (chromosome 21) were colocalized with eQTLs linked to increased expression of the neighboring gene IL10RB in NK cells and T-cell subsets (rs12482556, adj." (PMID 34799557, 2021). "The A allele at rs2834167, which is associated with lower IL10RB gene expression but higher plasma IL-10RB, was inversely associated with COVID-19 (per-A-allele OR= 0.91; 95%CI= 0.87-0.95; P=5.3×10-5)." (PMID 33837377, 2021). "Additionally, interleukin 10 receptor, IL10RB, was identified to be significant to patients’ severity and has been previously noted as a regulator of host susceptibility to COVID-19 severity and potential drug target." (PMID 37047222, 2023). "Data must still be carefully appraised for possible false positives, as may be the case with IL10RB being estimated protective in cultured fibroblasts for all outcomes but increasing the risk of COVID-19 outcomes in the tibial nerve for all outcomes." (PMID 37640912, 2023). "Using a translational genomics approach that integrates COVID-19 genetic susceptibility variants, multi-tissue genetically regulated gene expression (GReX), and perturbagen signatures, we identified IL10RB as the top candidate gene target for COVID-19 host susceptibility." (PMID 36064543, 2022). "IL10RB was predicted to be significantly upregulated in individuals susceptible to COVID-19 hospitalization, with downregulation predicted to significantly antagonize the polygenetically driven gene expression differences associated with COVID-19 hospitalization." (PMID 36064543, 2022). "Interestingly, a genetic association of variants of the IL10Rb gene with critical COVID-19 was recently identified through whole genome sequencing." (PMID 36451808, 2022). "Competitive pathway enrichment analysis demonstrated that overexpressing IL10RB in uninfected cells leads to the induction of COVID-19 relevant pathways implicated in vascular, immune system, and extracellular matrix processes, which were also activated by SARS-CoV-2 infection." (PMID 36064543, 2022). "One of the main challenges of our analysis was to determine whether IFNAR2 or IL10RB (or both) was driving the association with COVID-19 hospitalization, given that they share cis-eQTLs used as proposed instruments for our MR analysis." (PMID 33837377, 2021). "TWAS also confirmed the association of COVID-19 severity with increased expression of IL10RB." (PMID 34799557, 2021).
COVID-19 (continued). "H3K27ac HiChIP-based chromatin-interaction maps in NK cells showed that multiple cis-regulatory regions, including the IFNAR2 promoter, harbor COVID-19-risk eQTLs and directly or indirectly interact with the IL10RB promoter and potentially influence its expression." (PMID 34799557, 2021). "For the long-COVID predictive mixed model, the variables included were anosmia, fever, fatigue, COVID-19 clinical severity and presence of rs8178521 in the IL10RB gene." (PMID 38605121, 2024). "TYK2 and IL10RB are in Type III interferon signaling, and IL10RB is the top key regulator of COVID-19 host susceptibility." (PMID 37886583, 2023). "The levels of IL10RB expression gradually increased with disease severity with a higher effect size in the most severe COVID-19 patient group (end-organ damage) against all other groups." (PMID 36064543, 2022). "By performing a MAGMA gene-level association analysis, we observed that 25 genes including CXCR6, CCR1, IFNAR2, IL10RB, and OAS1 were significantly associated with severe COVID-19 (FDR < 0.05)." (PMID 35172892, 2022). "First, the index SNP for COVID-19 susceptibility in 21q22.11, rs130507285, falls within an intronic region of IFNAR2 (less than 24kbp from IL10RB)." (PMID 36064543, 2022). "We provide evidence from in vitro, in vivo, and retrospective epidemiological studies that validate the association of the top candidate gene, interleukin 10 receptor subunit beta (IL10RB), with COVID-19 outcome severity." (PMID 36064543, 2022). "Receptors for type I (IFNAR1 and 2) and III (IL10RB) interferons drive inflammation mediated by NK and CD8+ T cells, and IL-10RB binds IL-10 whose levels are a severity predictor in COVID-19." (PMID 35659055, 2022). "We found significant Mendelian randomization results for three proteins (ACE2: P=1.6×10-6, IFNAR2: P=9.8×10-11, and IL-10RB: P=2.3×10-14) using cis-eQTL genetic instruments that also had strong evidence for colocalization with COVID-19 hospitalization." (PMID 33837377, 2021). "Of these age-correlated proteins, six had been also associated with COVID-19 severity: HGF and CXCL9 shown the highest coefficients while IL10RB, VEGFA, IL-6 and TNF showed low albeit significant correlation (r < 0.30)." (PMID 34335580, 2021). "Additionally, the effects of the IFNAR2 and IL10RB gene products in the COVID-19 affected lungs were detected." (PMID 38455043, 2024). "In addition, we performed a GReX-based phenome-wide association study (PheWAS) to further understand the effect of IL10RB on pre-existing relevant phenotypes (before the emergence of COVID-19)." (PMID 36064543, 2022). "A summary data-based Mendelian randomization (SMR) analysis and a transcriptome-wide association study (TWAS) were performed for the severe COVID-19 dataset, and seven novel genes for severe COVID-19 were identified, including CCR5, CCR5AS, IL10RB, TAC4, RMI1, and TNFSF15." (PMID 36483456, 2022). "However, both IL10RB and IFNAR2 GReX are associated with more severe COVID-19 clinical outcomes in EUR, participants of African descent (AFR), and in the trans-ethnic meta-analyses (ordinal logistic regression)." (PMID 36064543, 2022). "‘Interleukin-10 signalling’ pathway variants in IL10RB, CCR2 and CCR5 were also enriched in PRSe2 and may contribute to the development of severe COVID-19." (PMID 35770811, 2022). "In our approach, IL10RB was prioritized primarily because its downregulation in cell lines reverses the GReX signature of COVID-19 and, secondarily, because it has a more uniform imputed transcriptional dysregulation across tissues (predominant downregulation)." (PMID 36064543, 2022). "These three cis-pQTLs, while possibly functional variants altering plasma IL-10RB levels, suggest that the plasma IL-10RB levels are not likely the mediator of the association between this locus and COVID-19 hospitalization." (PMID 33837377, 2021).
COVID-19 (continued). "To disentangle the shared eQTL signal for IL10RB and IFNAR2, we conducted phenome-wide association scans and pathway enrichment analysis, which suggested that IFNAR2 is more likely to play a role in COVID-19 hospitalization." (PMID 33837377, 2021). "In addition, the rs28368148 (CG genotype) correlating with the interferon-alpha-10 (IFNA10) gene was found strongly correlating with severe COVID-19, whereas the rs8178521 (CT genotype) of the IL-10-receptor-beta (IL-10RB) gene was found weakly correlated with severe COVID-19." (PMID 36941580, 2023). "Based on a large-scale meta-analysis (N = 680,128), our group found that the IFNAR2-IL10RB gene cluster was significantly associated with COVID-19 susceptibility, and suggested that IFNAR2 and IL10RB might have regulatory roles in the pulmonary immune response based on scRNA-seq data." (PMID 35172892, 2022). "To enhance granularity and phenotyping depth of IL10RB GReX association with COVID-19 associated hospitalization, we determined whether predicted upregulation of blood IL10RB was a good predictor of COVID-19 outcome severity and death in individuals who tested positive for SARS-CoV-2." (PMID 36064543, 2022). "IL-10RB and IFNAR2 are encoded by adjacent genes and some cis-eQTLs for IL10RB are also cis-eQTLs for IFNAR2, making it difficult to determine which gene may be responsible for the association with COVID-19 and requiring further investigation." (PMID 33837377, 2021). "The genetic liabilities to elevated blood pressure and to severe COVID-19 intertwine, and among them, the immune-regulating receptors CCR1/CCR5 and IL10RB signaling pathway are highlighted in the common effective tissue of the lung." (PMID 36160003, 2022). "Analysis of molecular networks commonly affected both by hypertension and by severe COVID-19 highlighted CCR1/CCR5 and IL10RB signaling, as well as Th1 and Th2 activation pathways, and also a potential for a shared regulation with multiple sclerosis." (PMID 36160003, 2022). "Despite these limitations, this study has some consistency with a recent MR study searching systematically for COVID-19 druggable targets that homed in on drugs targeting ACE2 and IFNAR2 or IL10RB." (PMID 34911594, 2021). "Among them, serum levels of IL-10RB, FGF-19, and CCL-2 positively contributed to both hospitalized and critical COVID-19 conditions (OR: 1.10~1.16), while the other 4 proteins conferred risk on critical COVID-19 only (OR: 1.07~1.16), including EIF4EBP1, IL-7, NTF3, and LIF." (PMID 38455043, 2024). "Through COVID-19-relevant transcriptome and enrichment gene sets, seven druggable targets with COVID-19-relevant functions were identified, including CCR9, CXCR6, XCR1, IL10RB, OAS1, OAS2, and OAS3." (PMID 37886583, 2023). "This suggests that the increased IFNAR2 (but not IL10RB) levels observed in the most severe group of COVID-19 patients may reflect the increased likelihood of SARS-CoV-2 viremia in those patients." (PMID 36064543, 2022).
colitis (19 papers, 2012 to 2025). Inflammation of the colon. "In humans, mutations to the IL10RA and IL10RB genes have both been strongly associated with infant colitis associated with defects in downregulation of proinflammatory cytokine secretion by monocytes." (PMID 37600781, 2023). "Defects in IL-10RB are described to cause severe colitis, as several anti-inflammatory processes are regulated by IL-10 binding to the IL-10R and subsequent STAT3 phosphorylation and activation." (PMID 33804706, 2021). "Mutations in IL10 or the genes encoding its receptors IL10RA/IL10RB in humans were shown to cause autosomal recessive disease with CD-like colitis and GWAS studies have identified associations between these three genes and sporadic IBD." (PMID 30410494, 2018). "Three homozygous mutations in IL10RA and IL10RB were identified from 4 of 9 patients with early onset colitis." (PMID 29118930, 2017). "Three homozygous mutations in IL10RA and IL10RB were identified in four out of nine patients with early onset colitis." (PMID 29118930, 2017). "As far as CD is concerned, the relevance of the IL-10 pathway in dampening inflammation was substantiated by the development of severe colitis in infants with mutations of IL-10, IL-10RA, or IL-10RB genes and in mice deficient in IL-10 that underwent spontaneous development of colitis." (PMID 26206376, 2015). "IL-10 is particularly relevant in IBD, as evidenced by the spontaneous development of colitis in Il10-/- and Il10Rb-/- mice and the correlation of SNPs in IL10 with the early onset of colitis." (PMID 40243612, 2025). "As defects in the IL-10R and IL-10 signaling on macrophages play a major role in causing severe colitis in patients, the generated VEO-IBD patient-derived iPSC clones were differentiated into macrophages for the detailed analysis of the IL-10RB defect." (PMID 33804706, 2021). "Conditional deletion of Il10ra in MNP (Cx3cr1-IL10raΔ) and Il10rb-/- mice leads to development of spontaneous colitis, similar to that observed in Runx3Δ mice." (PMID 32453801, 2020). "Comparison of RM DEGs in Runx3Δ with those in Il10raΔ and Il10rb-/-, which also induce colitis, revealed a gain of pro-inflammatory hallmarks in all three models of spontaneous colitis." (PMID 32453801, 2020). "While MNP-Runx3Δ and MNP-Il10RΔ mice displayed a similar spontaneous colitis phenotype with a significant overlap of RM up-regulated genes, expression of Il10ra and Il10rb was unaffected in Runx3Δ RM." (PMID 32453801, 2020). "Polymorphisms in genes encoding for subunits of the IL-10 receptor (IL10RA, IL10RB) are also associated with human IBD, particularly very early onset colitis." (PMID 29118930, 2017). "By the fourth week, more than 80% of Il10rb-/- mice exhibited moderate colitis with crypt abscesses and crypt hyperplasia, and virtually all mice displayed histologic signs of colitis by 8 weeks of age." (PMID 28678006, 2017). "Clodronate-containing liposomes significantly inhibited the histological signs of colitis in 3–4 week old Il10rb-/- mice compared to those treated with control liposomes." (PMID 28678006, 2017). "To identify the onset of colitis in IL10R deficiency, we examined the kinetics of intestinal inflammation from early post-natal life through adulthood in Il10rb-/- mice (129SvEv background) under specific pathogen-free (SPF) conditions." (PMID 28678006, 2017). "In this study, we triggered colitis by co-housing antibiotic pre-treated dnKO mice with untreated IL10rb+/− littermates." (PMID 25478789, 2014). "The investigators identified three distinct homozygous mutations in genes IL10RA and IL10RB, encoding the IL10R1 and IL10R2 proteins in four out of nine patients with early-onset colitis." (PMID 24454343, 2013).
colitis (continued). "The crucial role of IL-10 within the colonic mucosa is evidenced by infants carrying mutations in IL10 (interleukin 10), IL10RA (interleukin 10 receptor subunit alpha) or IL10RB (interleukin 10 receptor subunit beta), who develop severe colitis within the first weeks of life." (PMID 41010030, 2025). "Notably, in Il10rb KO mice, Tregs have normal development and suppressive function; however, Il10rb KO Tregs that are transferred into Rag1 KO mice along with effector T cells cannot prevent colitis." (PMID 37197653, 2023). "As expected, 4 week old Il10rb-/- mice maintained on regular water developed moderate colitis." (PMID 28678006, 2017). "At this age, endoscopic imaging and clinical scores revealed severe colitis in Il10rb-/- mice." (PMID 28678006, 2017). "To investigate the role of STAT1 signaling in T-cell driven colitis, we adoptively transferred unfractionated WT or Stat1−/− CD4+ T cells into Il10rb−/−Rag1−/− mice." (PMID 30796216, 2019). "We and others recently described the importance of IL-10R signaling in macrophages in the prevention of colitis, with Il10rb−/−Rag1−/− mice but not Rag1−/− mice developing colitis upon reconstitution with WT CD4+ T cells." (PMID 30796216, 2019). "We next asked if Stat1−/− T cells were able to induce colitis in the absence of NK cells by transferring them into NK cell-depleted Il10rb−/−Rag1−/− mice." (PMID 30796216, 2019).